APOE (apolipoprotein E)
Diseases named in the same sentence as APOE in open-access papers (continued):
Sharing a sentence is not in itself a finding about the gene and the disease.
dementia (continued). "The lower risk of dementia in ASPREE is likely influenced by the selection of healthy participants, depletion of deleterious APOE ε4 alleles, and a relatively short follow‐up period where healthy selection effects have not yet dissipated." (PMID 34041846, 2021). "In sub‐group analysis, among APOE ε3/ε4 heterozygotes, PRS modified dementia risk, with CID increasing from 10.8% (CI 7.2–16.3) in the low PRS tertile to 17.8% (CI 13.2–23.8) in the high." (PMID 34041846, 2021). "APOE genotypes are associated with ischemic heart disease (IHD), several other cardiovascular diseases and dementia." (PMID 33927215, 2021). "In APOE genotype‐stratified analysis of CID, after adjusting for covariates and death as a competing event, ε4/ε4 genotype was significantly associated with dementia risk (HR 6.38 [CI 3.8–10.7] p = 2.0 × 10−12) compared with ε3/ε3." (PMID 34041846, 2021). "To address some of these limitations, we examined the relationship of homozygotes and heterozygotes APOE ε4 with cognitive decline from midlife to old age and incident dementia." (PMID 33397450, 2021). "Because the APOE locus has been suggested as a potential modifier of COVID-19 disease, we added sensitivity analyses stratifying by dementia status or by disease severity." (PMID 34945790, 2021). "Dementia cases were generally older, more economically deprived, less educated, more likely to smoke, less physically active, more likely to have stroke history and family dementia history, and more likely to be APOE ε4 carriers." (PMID 33748832, 2021). "A consistent association has been established between carriage of the apolipoprotein E (APOE) ε4 allele and elevated risk of dementia or AD." (PMID 33748832, 2021). "Further studies with large populations and longer follow‐up are required to understand interactions between APOE and PRS in modifying dementia risk." (PMID 34041846, 2021). "In conclusion, our study found that APOE genotypes and PRS effect the relative risk of dementia in a population of healthy older individuals followed prospectively." (PMID 34041846, 2021). "The presence of at least one allele of apolipoprotein E (APOE) ε4 is a riskfactor for cardiovascular diseases and increases the risk of dementia in subjectswho have suffered a stroke, being particularly pronounced factors in the Latino population." (PMID 33907599, 2021). "In this study, we investigated the association of SNPs in the APOE and MAPT loci with time to dementia by retrospective survival analysis in neuropathologically defined PD brain donors." (PMID 33613437, 2021). "The underlying mechanisms linking APOE and MAPT variants to dementia are unclear, however neuropathological studies suggests that protein aggregation is pivotal in this association." (PMID 33613437, 2021). "We found that APOE ε4 and high PRS were associated with increased relative risk of dementia, but overall, cumulative incidence of dementia was low across all genotype groups." (PMID 34041846, 2021). "Prevalent and incident dementia and cognition, adjusted for potential confounders, including age, sex, diabetes, educational level, APOE ε4 carrier status, smoking, and estimated glomerular filtration rate." (PMID 33416887, 2021). "The progressive MCI group had a significantly higher proportion of APOE ε4 allele-carriers, lower MMSE scores and higher clinical dementia rating sum of boxes (CDR-SB) scores at baseline." (PMID 34465370, 2021). "Previous studies on LTL associations with AD and age-related cognitive decline, a possible prodromal symptom of dementia, have observed interactions between LTL and APOE ε4, such that LTL is more strongly associated with AD in APOE ε4-carriers." (PMID 34266503, 2021). "Cumulative incidence of dementia to age 85 years was 7.4% in all participants, 12.6% in APOE ε3/ε4 and 26.6% in ε4/ε4." (PMID 34041846, 2021).
dementia (continued). "A recent study suggested that the relation between ApoE ε4 and CVD can also determine the risk and prevalence of dementia; however, data have many gaps and have been deemed inconsistent." (PMID 35011591, 2021). "In this study we explored the genetic effects of MAPT and APOE on onset of dementia in PD in a neuropathologically characterized cohort." (PMID 33613437, 2021). "The GR@ACE/DEGESCO dementia configuration allows us to study, in a different population, the APOE effect suggested by previous studies with the UK Biobank on COVID-19 disease or in a Spanish elderly cohort." (PMID 34945790, 2021). "White APOE ε4 carriers had a similar age of dementia diagnosis of 83.3 and 83.4 years for males and females, respectively, yet demonstrated differing ages for non-ε4 carriers." (PMID 34744974, 2021). "This is such an important factor that even most studies involving tracing APOE to dementia are done with female mice." (PMID 34566624, 2021). "Consistent with our results, a previous study of PD patients demonstrated earlier development of dementia among APOE ε4-carriers (HR 1.90, 95% CI 1.05–3.44)." (PMID 33613437, 2021). "In the P301S-tau transgenic dementia mouse model, mice carrying human APOE4 exhibited more significant brain atrophythan mice carrying other APOE variants, such as APOE2 and APOE3." (PMID 33897406, 2021). "The graphical modelling showed that the presence of dementia was more likely to be associated with a higher VSRAD score, the presence of ApoE ε4, female sex, less years of education, and metabolite concentrations." (PMID 32424166, 2020). "The apolipoprotein E (APOE) ε4 allele is the strongest genetic risk factor for late onset AD and is also overrepresented in pure DLB and PD with dementia." (PMID 32912321, 2020). "The objective of the study is to determine the predictive value of additive and multiplicative interactions of NPS and APOE ε4 status on the prediction of incident dementia among MCI patients monitored in a Memory Clinic." (PMID 33208795, 2020). "We recommend removing the APOE region from polygenic score calculation and treating the APOE locus as an independent covariate when modeling dementia." (PMID 33143703, 2020). "This is in line with the previous study showing that low control, a component of passive jobs, magnified the impact of APOE ɛ4 on dementia." (PMID 32081835, 2020). "No statistical interaction was observed between telmisartan and APOE ε4 allele on the changes in MMSE, MoCA, DRS, CDR, and IQCODE and in the incidences of dementia (all Padjusted > 0.05)." (PMID 32581766, 2020). "In this study analyzing the association of apoE level in HDL with cognition and dementia, substantial differences existed based on the presence or absence of other apolipoproteins in the HDL fractions." (PMID 32648923, 2020). "Second, this sample community-dwelling older adults are well-characterized with rigorous adjudication of cognitive impairment, including dementia, and APOE e4 genotype." (PMID 33195297, 2020). "A combination of faecal ammonia and lactic acid concentration was indicative of the presence of dementia and had the same or slightly lower predictive accuracy as traditional biomarkers of dementia, including ApoE ε4 and VSRAD scores." (PMID 32424166, 2020). "The HR for dementia per 1-SD higher concentration of apoE in HDL that contained apoC3 was 1.11 (95% CI, 0.98-1.25) and was 0.87 (95% CI, 0.76-1.00) for apoE in HDL that lacked apoC3." (PMID 32648923, 2020). "The bidirectional stepwise MLR analysis indicated that baseline age, education, APOE‐ε4, peppermint, banana, pineapple, and MMSE were statistically significantly associated with incident dementia." (PMID 32864870, 2020). "Among the younger-old, there was an interaction between APOE ɛ4 and passive jobs in terms of dementia occurrence." (PMID 32081835, 2020).
dementia (continued). "In the full model, age, APOE-ε4, peppermint, pineapple, banana, and MMSE are statistically significantly (at the two-sided type one error α = 0.05 level) associated with dementia incidence." (PMID 33005146, 2020). "By interrogating the UKB, Kuo and co-workers found that ApoE ε4 homozygous individuals are more likely to be COVID-19 test positives compared with ε3 homozygotes, independently from dementia." (PMID 32917282, 2020). "These two groups varied significantly by frequency of AD, cerebral amyloid angiopathy (CAA), and dementia such that the APOE ε4 carriers group had a higher prevalence." (PMID 32076055, 2020). "With this taken together, APOE-targeted therapeutic strategies remain a propitious area of research for preventing or delaying the onset of AD type dementias." (PMID 32005122, 2020). "Systematically exploring all possible combinations of global variables, we found that global cognition together with APOE rendered the best two-variable model for predicting future dementia (AUC = 0.900)." (PMID 32925047, 2020). "Regarding other dementias, high CSF apoE concentrations were observed in DLB and PD relative to controls." (PMID 32054532, 2020). "Our study indicated that age, ApoE ε4 status, higher-levels of Aβ1–42 in plasma NDEs and lower SS-16 scores predicted the AD dementia conversion in individuals with MCI patients with modest accuracy." (PMID 32741361, 2020). "To date, very few studies have been focused on the impact of the convergence of neuropsychiatric symptoms (NPS) and APOE ε4 on the conversion to dementia in patients with Mild Cognitive Impairment patients (MCI), and none has been based in a clinical setting." (PMID 33208795, 2020). "As expected, individuals with incident dementia were older, had a lower education level, and were more often APOE ε4 carriers (all P < .01)." (PMID 31736136, 2020). "In contrast, apoE in HDL that contained apoC3 was unassociated with cognitive function and risk of dementia or AD." (PMID 32648923, 2020). "We nevertheless aimed at a more detailed understanding of the age-related modulations of our APOE effects, which is crucial to evaluate the possible implications of our findings for preclinical dementia diagnosis." (PMID 32923622, 2020). "The exact pathophysiology leading to dementia is still uncertain, but the apolipoprotein E (APOE) ε4 genotype plays a major role." (PMID 32460813, 2020). "Our results show an independent influence of APOE ε4, diabetes, heart disease, stroke, and delirium on dementia incidence across 8 years in older adults aged between 70 and 74 years." (PMID 32767997, 2020). "In both groups, incident dementia cases were less educated, more likely to carry APOE ɛ4, and had a lower baseline MMSE score." (PMID 32081835, 2020). "To clarify how specific the methylation changes detected are in dementia, we examined the methylation levels of APOE and CLU in blood samples of control, AD, dementia with Lewy bodies (DLB), vascular dementia (VaD), and frontotemporal dementia (FTD)." (PMID 32991610, 2020). "A global model (global cognition, APOE, total brain tissue volume: AUC = 0.920) rendered the highest predictive value for future dementia." (PMID 32925047, 2020). "Dementia is a disorder with a strong genetic locus of effect (APOE) and substantially weaker effects are scattered throughout the genome." (PMID 33143703, 2020). "In the three Caribbean islands being an APOE-ε4 carrier increases the risk to develop dementia by two folds (SHR 2.03 [1.32-3.11]); in Caucasian populations the risk among APOE-ε4 carriers is 10 to 15 times higher than in non APOE-ε4 carriers." (PMID 33537283, 2020). "Other major strengths of this study are the detailed, frequent, and prospective evaluation of neurological status, the substantial number of participants with dementia, and the comprehensive data available for adjustment, including by APOE genotype." (PMID 32648923, 2020).
dementia (continued). "Two of the previous studies, which had adjusted for APOE genotype, being the strongest single genetic marker related to development of dementia, also supported that conclusion." (PMID 32041683, 2020). "We found that APOE ε4, diabetes, heart disease, stroke, and delirium, independently considered, produce a significant increase in the cumulative incidence of dementia." (PMID 32767997, 2020). "Data on several AD-related factors were available in these existing cohorts, including age, sex, education, APOE genotype, family history of dementia, subjective cognitive decline (SCD), and memory tests, as well as on common exclusion criteria." (PMID 31907067, 2020). "In the stepwise model, age, weight, education, APOE-ε4, peppermint, banana, pineapple, and MMSE are associated with dementia incidence." (PMID 33005146, 2020). "Synergistic interactions between NPS and APOE ε4 are identified among MCI patients when predicting incident dementia." (PMID 33208795, 2020). "This study identifies, in a Memory Clinic setting, additive interactions between depression, apathy, anxiety, agitation, appetite, and irritability and APOE ε4 as predictors of conversion to dementia in MCI patients." (PMID 33208795, 2020). "The objective of the present study is to determine the effect of interaction of NPS and APOE ε4 on conversion to dementia in a large sample of MCI patients, controlling for several relevant clinical factors." (PMID 33208795, 2020). "With the current emerging knowledge on the regulation and function of brain insulin signaling, there is a need for further research into how insulin/glucose metabolism intersects with dementia in APOE isoform-dependent manner." (PMID 32005122, 2020). "Of all dementia cases, 76 (23.8%) had the diagnosis of clinical AD dementia, and 130 (40.6%) had APOE‐ε4." (PMID 32187654, 2020). "Numerous clinical studies have proposed that a low level of apolipoprotein E (APOE) genotype along with its genetic variations increases the risk of dementia; especially for individuals where dementia has been diagnosed in first-degree relatives." (PMID 33066592, 2020). "Specifically, we found that the older dropout group showed reduced offline episodic memory, had a higher proportion of APOE-ε4 carriers, and included several who progressed to manifest dementia over the next 4-year period." (PMID 31680849, 2019). "In contrast to APOE, we observed some contribution of family history of dementia and diastolic blood pressure to hippocampal ISOSF, but these effects did not survive multiple comparison correction." (PMID 30705365, 2019). "For example, the probability of dementia in APOE ε3ε4/ε4ε4 carriers with a PBV 0.3 units higher was equal to that of APOE ε3ε3 carriers, and with a PBV 0.6 units higher it was equal to that of APOE ε2ε3 carriers." (PMID 31022959, 2019). "The results of these analyses indicate that the net effect of APOE genotype on cognition and the prevalence of dementia is dependent upon the plasmalogen status of the person." (PMID 31022959, 2019). "For those with one or more copies of the ApoE-ε4 allele, level of IGF-I receptor stimulating activity was positively associated with dementia risk." (PMID 30809143, 2019). "In total, 50.3% (86 out of 171) of the patients with available APOE genotype data were ε4 carriers, and 38.9% (119 out of 306) had a family history of dementia." (PMID 31805990, 2019). "Cedazo-Minguez A had similar opinion that risk factors for AD included advanced age, family history of dementia, low educational accomplishment and presence of the ε4 isoform of the apolipoprotein E (apoE)." (PMID 31266451, 2019). "In our study, of all the outcomes, dementia had the strongest association with the CAA score after adjusting for cardiovascular factors and APOE-ε2/ε4 carriership [HR 3.25, 95% CI (1.00–10.54)]." (PMID 31866930, 2019). "Dementia status, age, sex, APOE genotype, level of intellectual disability, health variables, and living situation." (PMID 30452522, 2019).
dementia (continued). "The APOE genotype consistently predicted AD- or amyloid-related pathologies at death on average 6 years later, but with a different pattern than for incident dementia." (PMID 30670070, 2019). "In the final model, including APOE genotype, multimorbidity, living situation and early-onset epilepsy, the influence of sex on dementia diagnosis was lost." (PMID 30452522, 2019). "In univariable analyses, SBP and APOE ɛ4 were associated with risk of recurrent ICH, small vessel ischaemic stroke, incident dementia, incident depression and incident gait impairment." (PMID 32954261, 2019). "Our results demonstrate the possibility of utilizing APOE genotypes in combination with plasma Aβ1–42 levels as a pre-screening tool for predicting the positivity of amyloid PET findings in early stage dementia patients." (PMID 31881963, 2019). "We demonstrate that APOE ɛ4 interacts with BP following primary ICH to increase the risk for recurrent ICH, small vessel ischaemic stroke, incident dementia and incident gait impairment." (PMID 32954261, 2019). "The modified Boston criteria score showed higher risk for developing dementia with a score of 2 (probable CAA) and for death with a score of 1 (possible CAA) after adjusting for cardiovascular risk factors and APOE-ε2/ε4 carriership." (PMID 31866930, 2019). "Synapse losses can be documented with the first clear-cut evidence for dementia that are accompanied by synaptic toxicities conferred by APP and APOE mutations." (PMID 30902061, 2019). "After censoring for dementia, effect estimates remained similar for APOE-ε2 (HR 0.95,0.90–1.01), but attenuated for APOE-ε4 (HR 1.07,1.01–1.12)." (PMID 31356640, 2019). "This suggests that, in ApoE-ε4 carriers, there is a certain threshold above which IGF-I receptor stimulating activity becomes associated with dementia at long-term follow up." (PMID 30809143, 2019). "Long-term associations of a large SBP variation with an increased dementia risk were observed for both large rises and large falls in SBP after adjusting for age, sex, education, APOE genotype, vascular risk factors, and history of cardiovascular disease." (PMID 31714941, 2019). "The Pearson correlation between FAQ score and APOE 4+T+ group indicated that APOE 4 and CSF T-Tau were both possible factors for dementia." (PMID 31440157, 2019). "Covariates and interaction factors will include age, education, socio-economic status, physical activity, Apolipoprotein E ε4 genotype, family history of dementia or cognitive impairment, and lifestyle factors." (PMID 31077187, 2019). "After correcting for APOE genotype and demographic variables, biomarkers of PBV and the ratio of HDL-R were independently associated with cognition and dementia with PBV having a magnitude of association similar to that of APOE genotype." (PMID 31022959, 2019). "Results were similar after further adjustment for APOE genotype, and when excluding participants who developed dementia of any subtype within the first six months of follow-up." (PMID 30830563, 2019). "There was a correlation between TREM2-T, HLA-DR-A, Tau-H1, and ApoE-ɛ4 (T-A-H1-ɛ4) and a high-risk of dementia in contrast to TREM2-C, HLA-DR-G, Tau-H2, and ApoE-ɛ2 haplotype, which was protective (C-G-H2-ɛ2)." (PMID 30909239, 2019). "Using a community sample of 1205 elderly persons, we investigated the associations and potential interactions between Apolipoprotein E (APOE) genotype and serum phosphatidylethanolamine (PlsEtn) on cognition and dementia." (PMID 31022959, 2019). "Particularly genetic variants tagging PICALM consistently associate with dementia in GWAS, and this signal is one of the most consistent after the ε4 allele of APOE (apolipoprotein E gene), an association first recognized in 1993 and since validated globally." (PMID 30830563, 2019).